CD99 (CD99 molecule (Xg blood group))
Diseases named in the same sentence as CD99 in open-access papers (continued):
Sharing a sentence is not in itself a finding about the gene and the disease.
infection (8 papers, 2019 to 2025). The state of being infected such as from the introduction of a foreign agent such as serum, vaccine, antigenic substance or organism. "Immunological cell adhesion and migration across endothelial barriers are influenced by CD99 signaling, and elevated activity in severe infections can outcome in insufficient immunological infiltration and tissue inflammation." (PMID 40910395, 2025). "Junctional proteins including JAM, PECAM-1 and CD99 are activated by ROS during infection and bind the leukocyte ligands such as MAC-1, leading to vascular permeability." (PMID 34025711, 2021). "We showed that CD99 is a new marker for human TFH cell heterogeneity, which is differentially expressed in vaccine and infection." (PMID 40926076, 2025). "In the squamous epithelium of ectocervix, infection promoted CADM, SEMA4, SEMA6, CD99, and JAM signaling, indicative of epithelial remodeling and barrier restoration." (PMID 41042872, 2025). "To further explore whether this phenomenon exists in other leukocytes, we used Jurkat cells and found that CD99 and CD99L2 were significantly downregulated after ATCC 33277 infection, as shown by both Western blotting and flow cytometry." (PMID 37199607, 2023). "The CD99 signaling network demonstrated increased activity in NK cell and Platelets, with significant connection with T cell:CD4+ effector memory, T cell:CD4+ central memory and Pre‐B cell CD34‐, emphasizing their capacity to contribute to inflammatory mediators' processes after infection." (PMID 40910395, 2025). "Interestingly, productive infection was not strictly required as noninfected bystander cells, and UV-inactivated ZIKV also significantly induced the overexpression of the adhesion-associated protein CD99." (PMID 31562326, 2019). "While the CD22-CD45 signaling in the healthy group, involved in the B cell maturation process was absent in the infected and recovered group, the CD99 and CADM1 signaling observed in the infected group were absent post- infection." (PMID 36532041, 2022).
adenocarcinoma (3 papers, 2008 to 2012). A common cancer characterized by the presence of malignant glandular cells. "In this case, pathologic examination revealed an adenocarcinoma-like mass exhibiting expression of Vimentin and CD99 as well as focal expression of CK." (PMID 23251173, 2012). "Importantly, neither the adenocarcinomas nor the BPH sections were stained by the control Ig fusion protein CD99-Ig (and other control proteins, data not shown)." (PMID 18478075, 2008). "The adenocarcinoma component was strongly positive for cytokeratin 7 and pancytokeratin, weakly positive for synaptophysin and CD56, and negative for carbonic anhydrase IX, CD99, CDX2, chromogranin, cytokeratin 20 and smooth muscle actin." (PMID 19523243, 2009). "The adenocarcinoma component was strongly and diffusely immunoreactive (3+, cytoplasmic staining) for CK7 and pancytokeratin; weakly and focally immunoreactive (1+, cytoplasmic staining) for CD56 and synaptophysin; and negative for CA-IX, CD99, CDX2, chromogranin, CK20 and SMA." (PMID 19523243, 2009).
hematologic malignancies (3 papers, 2016 to 2023). "Although CD99 overexpression is observed in various hematologic malignancies, CD99 haploinsufficiency could also perturb normal T cell apoptosis and cell adhesion and result in increased T cell survival and mobility." (PMID 27655702, 2016).
kidney diseases (2 papers, 2023 to 2024). "Furthermore, we observed a consistent and significant change in the abundance of several peptides that have been previously associated with the progression of kidney diseases, including alpha-1-antitrypsin, antithrombin-III (ATIII), CD99 antigen and uromodulin." (PMID 37930730, 2024).
skin disorder (1 paper, 2021). Any deviation from the normal structure or function of the skin or subcutaneous tissue that is manifested by a characteristic set of symptoms and signs. "CD99, the other key receptor expressed in myofibroblast, was implicated in skin disorders." (PMID 35047019, 2021).
CD99 also shares sentences with these, for which no sentence is quoted: alveolar rhabdomyosarcoma (4 papers); neuroendocrine tumors (4); germ cell tumor (3); schwannoma (3); carcinosarcoma (2); CNS tumors (2); lymphoid neoplasm (2); myopericytoma (2); nodular fasciitis (2); non-Hodgkin lymphoma (2); skin cancer (2); squamous cell carcinoma (2); thymic tumors (2); adamantinoma (1); adenoid cystic carcinoma (1); adrenal carcinoma (1); Alzheimer disease (1); angioleiomyoma (1); angiomatoid fibrous histiocytoma (1); asthma (1); B-cell CLL (1); B-cell lymphomas (1); benign tumours (1); biphasic mesothelioma (1); bone cancer (1); connective tissue disorder (1); cystic teratoma (1); dermatofibroma (1); dermatofibrosarcoma protuberans (1); desmoid tumor (1).
A further 43 diseases each share a sentence with CD99 in 1 paper.